TUBGCP5 (tubulin gamma complex component 5)
Description:
Component of the gamma-tubulin ring complex (gTuRC) which mediates microtubule nucleation. The gTuRC regulates the minus-end nucleation of alpha-beta tubulin heterodimers that grow into microtubule protafilaments, a critical step in centrosome duplication and spindle formation.
Synonyms: GCP5; KIAA1899
Tractability: Small molecule: a structure with a bound ligand is known. PROTAC: ubiquitination databases record sites on it.
Gene: Protein-coding gene on chromosome 15 (22,983,192 to 23,039,640, reverse strand). Ensembl gene ENSG00000275835.
Subcellular location: Cytoplasm, cytoskeleton, microtubule organizing center, centrosome
Subcellular location (Human Protein Atlas): Basal body; Centrosome; Cytosol; Primary cilium; Primary cilium transition zone
Pathways (Reactome):
Cell Cycle: Recruitment of NuMA to mitotic centrosomes; Recruitment of mitotic centrosome proteins and complexes
Gene Ontology:
Molecular function: microtubule binding; protein binding; gamma-tubulin binding; microtubule minus-end binding
Biological process: microtubule nucleation; meiotic cell cycle; mitotic cell cycle; spindle assembly; microtubule cytoskeleton organization
Cellular component: centrosome; gamma-tubulin ring complex; cytosol; gamma-tubulin complex; microtubule organizing center; spindle pole
Genetic constraint (gnomAD): Loss-of-function variants: 84 observed, 119.46 expected, observed/expected ratio (o/e) 0.7, 90% interval 0.59 to 0.84. The upper end of that interval is the gene's LOEUF score, 0.84, which puts it in group 3 of 6, group 1 being the genes least tolerant of losing a copy. Missense variants: 1,031 observed, 1,158.8 expected, observed/expected ratio (o/e) 0.89, 90% interval 0.84 to 0.94. Synonymous variants: 423 observed, 408.75 expected, observed/expected ratio (o/e) 1.03, 90% interval 0.95 to 1.12.
Homologues: Orthologues: chimpanzee TUBGCP5 (99% identical), rabbit TUBGCP5 (93% identical), pig TUBGCP5 (93% identical), dog TUBGCP5 (92% identical), rat Tubgcp5 (89% identical), mouse Tubgcp5 (88% identical), guinea pig TUBGCP5 (84% identical), tropical clawed frog tubgcp5 (78% identical), zebrafish tubgcp5 (72% identical), macaque TUBGCP5 (63% identical), Drosophila melanogaster Grip128 (20% identical). Paralogues in human: TUBGCP6 (23% identical), TUBGCP3 (15% identical), TUBGCP2 (12% identical), TUBGCP4 (10% identical).
Diseases named in the same sentence as TUBGCP5 in open-access papers:
TUBGCP5 is named in the same sentence as 30 diseases in open-access papers, as found by Europe PMC text mining. Sharing a sentence is not in itself a finding about the gene and the disease. The quoted sentences say what the papers report.
autism (8 papers, 2012 to 2022). Persistent deficits in social interaction and communication and interaction as well as a markedly restricted repertoire of activity and interest as well as repetitive patterns of behavior. "Cases VII and VIII present microdeletion of proximal genes (NIPA1, TUBGCP5) and show similar levels of motor and cognitive development, both have mild autism with normal intelligence quotient and motor and language development delay, noted from the first year." (PMID 28174603, 2017).
obsessive-compulsive disorder (7 papers, 2019 to 2025). A disorder characterized by the presence of persistent and recurrent irrational thoughts (obsessions), resulting in marked anxiety and repetitive excessive behaviors (compulsions) as a way to try to decrease that anxiety. "TUBGCP5 is highly expressed in the subthalamic nuclei, a region linked to obsessive-compulsive disorder and ADHD." (PMID 30583851, 2019). "Moreover, variants in TUBGCP5 are known to be related to obsessive-compulsive disorders." (PMID 35887798, 2022). "CYFIP1 stabilizes axon processes and dendritic complexity, while TUBGCP5 has been linked to ADHD and obsessive-compulsive disorder (OCD)." (PMID 40843057, 2025). "The tubulin gamma complex associated protein 5 (TUBGCP5) gene is related to neurobehavioral disorders, such as attention deficit hyperactivity disorder and obsessive-compulsive disorder." (PMID 34888324, 2021). "TUBGCP5 is also highly expressed in brain and has been associated with ADHD and obsessive-compulsive disorder (OCD)." (PMID 32066678, 2020). "The TUBGCP5 (tubulin gamma complex-associated protein 5) gene in this region is associated with ADHD and obsessive-compulsive disorder when disturbed." (PMID 31207912, 2019). "The TUBGCP5 gene is associated with ADHD and obsessive compulsive disorder (OCD)." (PMID 38784233, 2024). "Moreover, mutations in each gene were associated with different disorders: NIPA1 with autosomal-dominant hereditary spastic paraplegia, NIPA2 with childhood absence epilepsy, TUBGCP5 with ADHD and obsessive-compulsive disorder, and CYFIP1 with increasing susceptibility to ASD and with schizophrenia." (PMID 30583851, 2019).
Angelman syndrome (6 papers, 2015 to 2024). A neurogenetic disorder characterized by severe intellectual deficit and distinct facial dysmorphic features. "This region covered the TUBGCP5, CFYIP1, NIPA1 and NIPA2 genes, which were critical genes causing behavioral and academic differences in the Prader-Willi/Angelman syndrome." (PMID 38784233, 2024). "The less frequent microdeletion 15q11.2, containing four protein-coding genes (NIPA1, NIPA2, CYFIP1, and TUBGCP5), is associated with Burnside–Butler syndrome (BBS), which partially overlaps with certain neurodevelopmental disorders, including Prader-Willi and Angelman syndrome." (PMID 36553064, 2022). "It is adjacent to the Parder–William/Angelman syndrome imprinting area, and its size is approximately 500 kb, involving four OMIM genes: NIPA1, NIPA2, CYFIP1, and TUBGCP5, which are hot spots in clinical research." (PMID 38172840, 2024).
developmental delay (4 papers, 2020 to 2025). "The copy number variation (CNV) of 15q11.2, an emerging and common condition observed during prenatal counseling, is encompassed by four highly conserved and non-imprinted genes—TUBGCP5, CYFIP1, NIPA1, and NIPA2—which are reportedly related to developmental delays or general behavioral problems." (PMID 34680874, 2021).
microcephaly (4 papers, 2019 to 2025). A congenital or acquired developmental disorder in which the circumference of the head is smaller than normal for the person's age and sex. "In humans, an association between a TUBGCP5 missense variant and microcephaly, which is a severe anomaly, has been shown." (PMID 34915862, 2021). "Gamma-complex component genes (TUBGCP4, TUBGCP5, and TUBGCP6) are critical in neuronal progenitor proliferation, and its variants cause cell proliferation defects and increased apoptosis, which have been reported to be associated with microcephaly." (PMID 40017707, 2025).
fragile X syndrome (3 papers, 2020 to 2023). A genetic syndrome caused by mutations in the FMR1 gene which is responsible for the expression of the fragile X mental retardation 1 protein. "In silico analyses for the four coding genes of NIPA1, NIPA2, CYFIP1, and TUBGCP5 in the 15q11.2 region suggested cardinal disease associations of NIPA1‐Spastic paraplegia 6, NIPA2‐PWS/AS, CYFIP1‐fragile X syndrome and autism, and TUBGCP5‐AS." (PMID 37013615, 2023).
Intellectual disability (2 papers, 2020 to 2023). "Both proband 15, a boy affected by TS, OCD, behavioral problems, and mild dysmorphic features, and proband 19, a girl affected by TS, mild intellectual disability, and ODD, presented the recurrent 15q11.2 deletion of about 395 Kb, which includes TUBGCP5, CYFIP1, NIPA1, and NIPA2 genes." (PMID 36833427, 2023).
sarcoma (1 paper, 2022). A usually aggressive malignant neoplasm of the soft tissue or bone. "In sarcoma, the mutation of tubulin gamma complex-associated protein 5 (TUBGCP5) gene reduced the expression of YY1." (PMID 35791393, 2022).
neurodevelopmental disorder (3 papers, 2012 to 2022). A behavioral and cognitive disorder with onset during the developmental period that involves impaired or aberrant development of intellectual, motor, or social functions. "In this study, we explored functions and interactions of the four protein-coding genes in this region, namely NIPA1, NIPA2, CYFIP1, and TUBGCP5, and elucidate their role, in solo and in concert, in the causation of neurodevelopmental disorders." (PMID 32384786, 2020).
TUBGCP5 also shares sentences with these, for which no sentence is quoted: attention deficit-hyperactivity disorder (5 papers); epilepsy (3); autism spectrum disorder (2); Prader-Willi syndrome (2); schizophrenia (2); breast tumors (1); cardiovascular diseases (1); childhood absence epilepsy (1); congenital heart disease (1); dementia (1); Dyscalculia (1); dyslexia (1); glioma (1); idiopathic generalized epilepsies (1); learning disability (1); obsessive-compulsive behavior (1); paraplegia (1); peripheral nervous system disease (1); psychosis (1); Spastic paraplegia (1); Spastic paraplegia 6 (1).